ERCC5 (ERCC excision repair 5, endonuclease)
Description:
Single-stranded structure-specific DNA endonuclease involved in DNA excision repair. Makes the 3'incision in DNA nucleotide excision repair (NER). Binds and bends DNA repair bubble substrate and breaks base stacking at the single-strand/double-strand DNA junction of the DNA bubble. Plays a role in base excision repair (BER) by promoting the binding of DNA glycosylase NTHL1 to its substrate and increasing NTHL1 catalytic activity that removes oxidized pyrimidines from DNA. Involved in transcription-coupled nucleotide excision repair (TCR) which allows RNA polymerase II-blocking lesions to be rapidly removed from the transcribed strand of active genes. Functions during the initial step of TCR in cooperation with ERCC6/CSB to recognized stalled RNA polymerase II. Also, stimulates ERCC6/CSB binding to the DNA repair bubble and ERCC6/CSB ATPase activity. Required for DNA replication fork maintenance and preservation of genomic stability. Involved in homologous recombination repair (HRR) induced by DNA replication stress by recruiting RAD51, BRCA2, and PALB2 to the damaged DNA site. In TFIIH stimulates the 5'-3' helicase activity of XPD/ERCC2 and the DNA translocase activity of XPB/ERCC3. During HRR, binds to the replication fork with high specificity and stabilizes it. Also, acts upstream of HRR, to promote the release of BRCA1 from DNA.
Synonyms: XPG; ERCM2; XPGC; COFS3; ERCC5-201; UVDR
Tractability: Small molecule: it belongs to a druggable protein family. PROTAC: ubiquitination databases record sites on it; its protein half-life has been measured; a small molecule that binds it is known.
Target class: Other nuclear protein
Gene: Protein-coding gene on chromosome 13 (102,845,831 to 102,875,995, forward strand). Ensembl gene ENSG00000134899.
Subcellular location: Nucleus; Chromosome
Subcellular location (Human Protein Atlas): Nucleoplasm
Pathways (Reactome):
DNA Repair: Dual Incision in GG-NER; Dual incision in TC-NER; Formation of Incision Complex in GG-NER
Gene Ontology:
Molecular function: bubble DNA binding; damaged DNA binding; DNA endonuclease activity; double-stranded DNA binding; endonuclease activity; enzyme activator activity; protein binding; protein homodimerization activity; protein-containing complex binding; RNA polymerase II complex binding; single-stranded DNA binding; catalytic activity; DNA binding; hydrolase activity, acting on ester bonds; nuclease activity
Biological process: base-excision repair, AP site formation; double-strand break repair via homologous recombination; negative regulation of apoptotic process; nucleotide-excision repair; response to UV; response to UV-C; transcription-coupled nucleotide-excision repair; DNA recombination
Cellular component: chromosome; DNA replication factor A complex; nucleoplasm; nucleotide-excision repair complex; nucleus; protein-containing complex
Genetic constraint (gnomAD): Loss-of-function variants: 68 observed, 108.63 expected, observed/expected ratio (o/e) 0.63, 90% interval 0.51 to 0.77. The upper end of that interval is the gene's LOEUF score, 0.77, which puts it in group 3 of 6, group 1 being the genes least tolerant of losing a copy. Missense variants: 1,360 observed, 1,478.6 expected, observed/expected ratio (o/e) 0.92, 90% interval 0.88 to 0.96. Synonymous variants: 541 observed, 550.78 expected, observed/expected ratio (o/e) 0.98, 90% interval 0.92 to 1.05.
Gene-disease validity (ClinGen):
ClinGen rates the evidence that ERCC5 causes each of these diseases.
xeroderma pigmentosum group G (autosomal recessive): Definitive.
Cancer hallmarks: escaping programmed cell death (promotes); genome instability and mutations (suppresses); genome instability and mutations (promotes)
Homologues: Orthologues: chimpanzee ERCC5 (98% identical), macaque BIVM (94% identical), dog ERCC5 (73% identical), mouse Ercc5 (66% identical), rat Ercc5 (62% identical), zebrafish bivm (3% identical), guinea pig Bivm (2% identical), dog BIVM (2% identical), rat Bivm (2% identical), mouse Bivm (2% identical), tropical clawed frog bivm (2% identical).
Diseases named in the same sentence as ERCC5 in open-access papers:
ERCC5 is named in the same sentence as 109 diseases in open-access papers, as found by Europe PMC text mining. Sharing a sentence is not in itself a finding about the gene and the disease. The quoted sentences say what the papers report.
xeroderma pigmentosum (56 papers, 2011 to 2026). Xeroderma pigmentosum (XP) is a rare genodermatosis characterized by extreme sensitivity to ultraviolet (UV)-induced changes in the skin and eyes, and multiple skin cancers. "ERCC5 is important for repairing DNA damage and has been linked to certain cancers and to the skin disease xeroderma pigmentosum." (PMID 40431601, 2025). "Other pathogenic variants were present in FANCE, XPA and ERCC5, associated with Fanconi anaemia, xeroderma pigmentosum (XP) group A and XP group G, respectively." (PMID 39315505, 2025). "Mutational defects in ERCC5 can cause either the cancer-prone condition xeroderma pigmentosum alone or in combination with the severe neurodevelopmental disorder Cockayne syndrome or the infantile lethal cerebro-oculo-facio-skeletal syndrome." (PMID 34113558, 2021). "Although rare, mutations in the ERCC5 gene have also been associated with the development of Cockayne syndrome in combination with xeroderma pigmentosum (US National Library of Medicine, National Institutes of Health 2014)." (PMID 27099827, 2016). "Some mutations of ERCC5, the gene coding for XPG, may give rise to a combined Xeroderma Pigmentosum and Cockayne Syndrome." (PMID 35802638, 2022). "DNA incision activity by XPG is missing in a group of patients with xeroderma pigmentosum (XP) with mutations in the ERCC5 gene coding for XPG protein." (PMID 34205418, 2021). "g.,ERCC2/XPD,ERCC3/XPB,ERCC4/XPF,ERCC5/XPG,ERCC6/CSB, andERCC8) in the NER pathway frequently cause Xeroderma pigmentosum, trichothiodystrophy, or Cockayne syndrome." (PMID 35593466, 2022). "The xeroderma pigmentosum, complementation group G (XPG/ERCC5) component of NER, as a complex with ERCC1, is a structure-specific endonuclease that makes the 3’ incision in DNA excision repair following UV-induced damage." (PMID 35052761, 2021). "The function of ERCC5 has been most widely investigated in xeroderma pigmentosum and DNA excision repair following UV-induced damage." (PMID 27099827, 2016). "The excision repair cross complementing group 5 (ERCC5) gene, also known as the xeroderma pigmentosum group G (XPG) gene, is an indispensable component of NER, which belongs to the flap structure-specific endonuclease 1 (FEN1) family." (PMID 22848513, 2012). "The NER factor excision-repair cross-complementation group 5 (ERCC 5)/xeroderma pigmentosum complementation group G (XPG) is a 3 ́endonuclease that helps to excise the UV-damaged DNA strand and stabilizes the NER DNA-repair and basal transcription factor, transcription factor II H (TFIIH)." (PMID 41563504, 2026). "Homozygous or compound heterozygous PVs in FANCC and ERCC5 are known to be linked to autosomal recessive disorders, Fanconi anemia complementation group C (MIM: 227645) and Xeroderma pigmentosum complementation group G (MIM: 278780), respectively, known to exhibit increased risk to cancer." (PMID 36969007, 2023). "Biallelic pathogenic variants in one of the seven NER genes coding for the so-called complementation groups, XPA, ERCC3, XPC, ERCC2, DDB2, ERCC4, ERCC5, the NER gene ERCC1, and the gene coding for XP variant, POLH, are the causes of the rare hereditary disease Xeroderma pigmentosum (XP)." (PMID 35174087, 2022). "TTD is a distinct condition from Xeroderma Pigmentosum (XP) caused by mutation in eight XP‐associated genes: XPA, XPD (ERCC2), XPB (ERCC3), XPF (ERCC4), XPG (ERCC5), XPC, XPE (DDB2), and a variant form related to the POLH gene." (PMID 39976384, 2025). "Several XP types exist, and the MeSH term Xeroderma pigmentosum VII corresponds to the group G, caused by mutations in the ERCC5 gene, and with symptoms that overlap Cockayne syndrome." (PMID 33888761, 2021). "Worth noting is the fact that the ERCC2/XPD and ERCC5/XPG proteins are both involved in excision repair of UV-induced DNA damage and that photosensitivity is commonly observed in patients with xeroderma pigmentosum, Cockayne syndrome, and trichothiodystrophy." (PMID 21496236, 2011).
xeroderma pigmentosum (continued). "Several xeroderma pigmentosum (XP) group genes are involved in NER, including group C (XPC), group D (ERCC2/XPD) and group G (ERCC5/XPG)." (PMID 27246611, 2016).
Cockayne syndrome (23 papers, 2011 to 2026). A multisystem condition characterized by short stature, a characteristic facial appearance, premature aging, photosensitivity, progressive neurological dysfunction, and intellectual deficit. "Mutations in ERCC5 lead to Cockayne Syndrome (CS), which is characterized by premature aging." (PMID 31921313, 2019). "Characteristic features of Cockayne syndrome include impaired nervous system development and mental retardation, highlighting the critical role ERCC5 plays in normal CF." (PMID 27099827, 2016). "Besides these major forms, several cases with specific minor mutations in ERCC3/XPB, ERCC2/XPD, and ERCC5/XPG display the combined features of XP and an orphan progeroid disorder, Cockayne syndrome (CS), termed XPCS." (PMID 37364129, 2023).
gastric cancer (18 papers, 2014 to 2024). A primary or metastatic malignant neoplasm involving the stomach. "In the past couple of years, the relationship between ERCC5 variants and gastric cancer risk drew much attention of researchers, especially for Chinese investigators." (PMID 36033436, 2022). "With the largest sample size thus far in present study, we acquired that three variants of ERCC5 were probably involved in carcinogenesis of gastric cancer, rs17655 in Caucasians and rs873601 in Asians was related to an increased risk." (PMID 36033436, 2022). "Briefly, our research offers comprehensive epidemiological evidence that common variants of the ERCC4 and ERCC5 genes show association with the predisposition of bladder cancer, esophageal cancer, laryngeal cancer, uterine cancer, and gastric cancer." (PMID 36033436, 2022). "According to the results, there might exist different causal variants and functional mechanisms in the relationships of variants in the ERCC5 genes with esophageal cancer, gastric cancer, laryngeal cancer, and uterus and cervical cancer predisposition." (PMID 36033436, 2022). "For instance, ERCC5 rs1047768 variant reduced the risk of gastric cancer, ERCC3 rs4150403 was associated with an increased susceptibility to head and neck cancer in Caucasians, and ERCC6 rs4253132 polymorphism decreased the risk of head and neck cancer among African Americans." (PMID 33557438, 2021). "Former study has reported that accumulation of these risk genotypes could reinforce the link between ERCC5 and gastric cancer risk, and some studies figured out that the Helicobacter pylori infection may enhance the genetic effect on altered gastric cancer risk." (PMID 36033436, 2022). "ERCC2 rs50871 G/T, ERCC6 rs1917799 G/T and DDB2 rs3781619 A/G polymorphisms were significantly associated with shorter OS, while ERCC1 rs3212961 A/C, ERCC5 rs2094258 A/G and DDB2 rs830083 C/G could predict favorable OS of gastric cancer patients." (PMID 35955506, 2022). "ERCC5, pertaining to the FEN1/XPG endonuclease family, is ectopically expressed in gastric cancer, breast cancer, scaly cell carcinoma and liver cancer." (PMID 35934844, 2022).
ovarian carcinoma (12 papers, 2009 to 2024). A malignant neoplasm originating from the surface ovarian epithelium. "According to other findings, ERCC5 was a novel prognostic indicator for predicting ovarian cancer survival and a potential target in platinum chemotherapy." (PMID 37189432, 2023). "A model that estimates the likelihood of ovarian cancer with the best association with outcomes was developed with nine proteins (P38MAPK, RAB11, FOXO3A, AR, BETACATENIN, Sox2, IGFRb, AKT_pS473, and ERCC5) using a LASSO–Cox algorithm." (PMID 37189432, 2023). "The other variant, ERCC5 (rs1047768, or T335C), has been studied in ACC and ovarian cancer patients." (PMID 19536092, 2009). "Additionally, in a study of ovarian cancer patients treated with platinum-based chemotherapeutic drugs, loss of heterozygosity (LOH) of ERCC5 and down regulation of this gene were associated with a favorable PFS, presumably due to increased efficacy of these drugs." (PMID 23626689, 2013). "Meanwhile, we applied fit Chi-square calculation to evaluate these mutations with ovarian cancer risk and found MC1R:c.359T>C, ERCC5:c.1586G>C and PRSS1:c.72C>T that significantly fails to conform Hardy-Weinberg equilibrium (P-value<0.05)." (PMID 38817903, 2024).
breast carcinoma (11 papers, 2012 to 2025). "The present study was designed to associate single nucleotide polymorphisms of ERCC5 (rs751402, rs2094258, rs17655, and rs873601) with breast cancer and associated risk factors." (PMID 36686735, 2022). "Genotyping frequency and correlation of ERCC5 germline variants with chemotherapeutic drugs in breast cancer patients." (PMID 36686735, 2022). "This is the first report of the association between ERCC5 (rs751402, rs2094258, rs17655, and rs873601) and breast cancer risk in Pakistan." (PMID 36686735, 2022). "Correlations between clinicopathological parameters and ERCC5 germline variants in patients with breast cancer (n = 430)." (PMID 36686735, 2022). "This study aimed to assess the role of four selected single nucleotide polymorphisms (SNPs) in ERCC5 and their linkage disequilibrium associated with survival analysis and clinical outcomes in breast cancer." (PMID 36686735, 2022). "GGT1 has a suggested function in pancreatic carcinogenesis, whereas NCOR1 is part of a corepressor complex with histone deacetylase 3 (HDAC3) and may act as an oncogene in thyroid cancer, while ERCC5 polymorphisms were reported in breast cancer." (PMID 35205822, 2022). "Furthermore, studies have suggested that ERCC5 SNPs are associated with development of some cancers, such as breast cancer and smoking-related cancers." (PMID 22815677, 2012). "Our study highlights the correlation of ERCC5 polymorphisms with various clinicopathological factors, overall survival rates with different survival functions, linkage disequilibrium analysis, and therapeutic outcomes of different chemotherapeutic drugs among breast cancer patients." (PMID 36686735, 2022). "Four SNPs (rs751402, rs17655, rs2094258, and rs873601) of the ERCC5 gene were analyzed using the PCR-RFLP technique, followed by sequencing in 430 breast cancer (BC) cases and 430 cancer-free individuals." (PMID 36686735, 2022). "However, our meta-analysis suggests that there is no statistical evidence for an association between the ERCC5 Asp1104His polymorphism and overall cancer risk, which is consistent with the previous two meta-analyses conducted in breast cancer and melanoma, respectively." (PMID 22815677, 2012).
colorectal cancer (10 papers, 2012 to 2022). A primary or metastatic malignant neoplasm that affects the colon or rectum. "In the present study, we also show that the TT genotype of the ERCC5 His46His polymorphism is associated with shorter DFS in the two colorectal cancer patient cohorts investigated." (PMID 23626689, 2013). "The main result of our study is that the associations of the MTHFR Glu429Ala polymorphism with the overall survival and the ERCC5 His46His polymorphism with the disease-free survival were detected in two separate cohorts of colorectal cancer patients." (PMID 23626689, 2013). "In this study, associations of the MTHFR Glu429Ala polymorphism with OS and the ERCC5 His46His polymorphism with DFS were identified in two colorectal cancer patient cohorts." (PMID 23626689, 2013). "Whether His46His polymorphism causes up-regulation or down-regulation of ERCC5 is presently unknown and functional characterization of the polymorphism is required to understand its potential prognostic role in colorectal cancer." (PMID 23626689, 2013). "The altered expression of ERCC genes has been associated with increased risk of colorectal cancer, where ERCC1, ERCC2 and ERCC5 were overexpressed, and invasive cervical carcinoma, where ERCC1 and ERCC2 were underexpressed." (PMID 35955506, 2022). "ERCC5 might be involved in the efficacy of oxaliplatin containing chemotherapy for advanced colorectal cancer." (PMID 23118991, 2012). "In patients with colorectal cancer ERCC1, ERCC2, ERCC5 and DDB2 genes are more expressed in tumor tissue than in matched normal tissue, while ERCC4 is downregulated." (PMID 35955506, 2022).